RN7SKP193 (RN7SK pseudogene 193)
Gene: Miscellaneous RNA gene on chromosome 14 (50,068,568 to 50,068,873, forward strand). Ensembl gene ENSG00000201358.
Homologues: Orthologues: chimpanzee 7SK (98% identical), guinea pig 7SK (56% identical), mouse Gm54766 (55% identical). Paralogues in human: RN7SKP90 (78% identical), 7SK (77% identical), RN7SKP176 (76% identical), RN7SKP9 (76% identical), RN7SKP203 (76% identical), RN7SKP79 (76% identical), RN7SKP180 (76% identical), RN7SKP71 (75% identical), RN7SKP255 (75% identical), RN7SKP6 (74% identical), RN7SKP189 (73% identical), RN7SKP204 (73% identical), and 284 more.